ZBTB2 (zinc finger and BTB domain containing 2)
Description:
May be involved in transcriptional regulation.
Synonyms: KIAA1483; ZNF437; bA351K16.2
Tractability: PROTAC: UniProt records ubiquitination sites on it.
Target class: Transcription factor
Gene: Protein-coding gene on chromosome 6 (151,364,105 to 151,391,696, reverse strand). Ensembl gene ENSG00000181472.
Subcellular location: Nucleus
Subcellular location (Human Protein Atlas): Cytosol; Nucleoplasm
Gene Ontology:
Molecular function: DNA-binding transcription repressor activity, RNA polymerase II-specific; identical protein binding; protein binding; RNA polymerase II cis-regulatory region sequence-specific DNA binding; sequence-specific double-stranded DNA binding
Biological process: negative regulation of transcription by RNA polymerase II; regulation of cytokine production; regulation of immune system process
Cellular component: nucleoplasm; nucleus
Genetic constraint (gnomAD): Loss-of-function variants: 2 observed, 35.08 expected, observed/expected ratio (o/e) 0.057, 90% interval 0.022 to 0.18. The upper end of that interval is the gene's LOEUF score, 0.18, which puts it in group 1 of 6, group 1 being the genes least tolerant of losing a copy. Missense variants: 328 observed, 586.84 expected, observed/expected ratio (o/e) 0.56, 90% interval 0.51 to 0.61. Synonymous variants: 215 observed, 227.67 expected, observed/expected ratio (o/e) 0.94, 90% interval 0.84 to 1.06.
Homologues: Orthologues: chimpanzee ZBTB2 (99% identical), macaque ZBTB2 (99% identical), rabbit ZBTB2 (99% identical), dog ZBTB2 (97% identical), pig ZBTB2 (96% identical), guinea pig ZBTB2 (96% identical), mouse Zbtb2 (95% identical), rat Zbtb2 (87% identical), tropical clawed frog zbtb2 (79% identical), zebrafish zbtb2b (51% identical), zebrafish zbtb2a (42% identical), zebrafish znfl2a (13% identical).
Diseases named in the same sentence as ZBTB2 in open-access papers:
ZBTB2 is named in the same sentence as 23 diseases in open-access papers, as found by Europe PMC text mining. Sharing a sentence is not in itself a finding about the gene and the disease. The quoted sentences say what the papers report.
gastric cancer (7 papers, 2012 to 2022). A primary or metastatic malignant neoplasm involving the stomach. "Overexpression of miR-149 can inhibit tumor cell proliferation and cell cycle progression by targeting ZBTB2 in gastric cancer cell lines, and it can inhibit tumor cell migration." (PMID 23826111, 2013). "As a tumor suppressor gene, miR-149 may inhibit proliferation and induce cell cycle arrest by targeting ZBTB2 in gastric cancer." (PMID 24040059, 2013). "Collectively, these results demonstrate, for the first time, that ZBTB2 may function as an oncogene in the tumorigenesis of gastric cancer." (PMID 23144691, 2012). "Moreover, our results show that ZBTB2 may function as an oncogene in the development of gastric cancer." (PMID 23144691, 2012). "Ectopic expression of miR-149 in gastric cancer cells inhibits proliferation and cell cycle progression by downregulating zinc finger and BTB domain containing 2 (ZBTB2)." (PMID 29337929, 2018). "Moreover, upregulation of other transcription factors such as Zinc finger and BTB domain-containing protein 2 (ZBTB2) and RUNX2 due to downregulation of miR-153 may also affect tumorigenicity of gastric cancer." (PMID 36158686, 2022).
bladder cancer (3 papers, 2019 to 2025). "Downregulation of miR-4316 in bladder cancer tissues elevates expression of ZBTB2." (PMID 37177979, 2023). "In addition, CALML3-AS1 is also one of the low-grade glioma immune-related lncRNAs we screened, and it has been reported to inhibit microRNA-4316 in bladder cancer, thereby upregulating ZBTB2 and promoting tumorigenesis of bladder cancer." (PMID 31419958, 2019).
colorectal cancer (3 papers, 2020 to 2023). A primary or metastatic malignant neoplasm that affects the colon or rectum. "ZBTB2 also was recently identified as a potential oncogene in a screen of colorectal cancers with microsatellite instability." (PMID 33635925, 2021). "Another potential imprinted gene (ZBTB2) is among the genes identified in approximately 15% of all colorectal cancers." (PMID 32475352, 2020).
viral infection (3 papers, 2013 to 2024). "For instance, the transcription factor Zfp384 (zinc finger protein 384), limiting cytokine/chemokine gene transcription in macrophages in response to viral infection, or Zbtb2 (zinc finger and BTB domain containing 2) inhibiting NF-κB activation were upregulated in KSRP-deficient BMDM." (PMID 38612694, 2024).
esophageal SCCs (2 papers, 2021). "As a newly identified miRNA, miR-488-3p was found as a tumor suppressor in esophageal squamous cell carcinoma and melanoma by respectively targeting ZBTB2 and PRKDC." (PMID 32862195, 2021).
papillary thyroid cancer (2 papers, 2021 to 2025). "In overall, we suggest that AUF1 may regulate the expression of ZBTB2 by binding to ZBTB2 3’-UTR, affecting the stability of ZBTB2 mRNA, which in turn affects the expression of TRIM58 and regulates the proliferation, migration, and invasion of papillary thyroid cancer cells." (PMID 34222000, 2021).
Ataxia (1 paper, 2021). Ataxia refers to impaired coordination of voluntary muscle movement. "This possibility is enhanced by strong links of ataxias to mutations in DNA damage response pathways, including ATR and ATM and our observations that the DNA damage response regulates ZASC1:ZBTB2 interaction." (PMID 33635925, 2021). "Based on the findings reported here, it is possible that dysregulation of ZASC1:ZBTB2:HDAC4 interactions contributes to these ataxias." (PMID 33635925, 2021).
bipolar disorder (1 paper, 2018). A disorder of the brain that causes unusual shifts in mood, energy, activity levels and the ability to carry out day-to-day tasks. "Meanwhile, eQTL data showed SNP rs852004 regulated the expression of ZBTB2 in cerebellum of bipolar disorder patients and human prefrontal cortex." (PMID 29769613, 2018).
breast carcinoma (1 paper, 2022). "TmPyP4 with an inhibitory effect on G-quadruplex formation could increase levels of miR-149 in breast cancer cells, leading to reduction of ZBTB2 expression and attenuation of cell proliferation." (PMID 35488342, 2022).
HIV-1 infection (1 paper, 2021). The type species of lentivirus and the etiologic agent of acquired immunodeficiency syndrome (AIDS). "To further verify that ZASC1 and ZBTB2 primarily affect HIV-1 gene expression and not other steps in HIV-1 infection, we took two approaches that do not rely on HIV-1 transcription." (PMID 33635925, 2021).
oral squamous cell carcinoma (1 paper, 2024). "Another study found that miR-4282 impeded tumor growth in oral squamous cell carcinoma cells by targeting LIN28B and downregulating ZBTB2, suggesting its potential as a novel biomarker for OSCC." (PMID 38532994, 2024).
ovarian carcinoma (1 paper, 2023). A malignant neoplasm originating from the surface ovarian epithelium. "The differential expression of CCDC170, MTRF1L, ZBTB2, ARMT1, PLEKHG1 and QRSL1 genes affected the overall survival (OS) of ovarian cancer patients." (PMID 37024829, 2023).
renal fibrosis (1 paper, 2024). A final common manifestation of a wide variety of chronic kidney diseases characterized by glomerulosclerosis and tubulointerstitial fibrosis. "Further investigations into the expression of APC and ZBTB2 in M2 macrophages hold promise for providing fresh insights into the mechanisms underlying renal fibrosis and facilitating the development of innovative therapeutic approaches to combat this disease." (PMID 39328595, 2024). "In addition, the expression of APC and ZBTB2 was significantly decreased in M2 macrophages from uremic patients, and APC and ZBTB2 were identified as potential renal fibrosis biomarkers associated with M2 macrophage infiltration." (PMID 39328595, 2024). "Additional in vitro and in vivo studies are necessary to investigate the specific mechanisms by which APC and ZBTB2 affect M2 macrophage infiltration in renal fibrosis." (PMID 39328595, 2024). "First, the study is retrospective; in-depth studies are needed to clarify the role of APC and ZBTB2 in renal fibrosis." (PMID 39328595, 2024). "This reduced expression of APC and ZBTB2 in M2 macrophages serves as a significant indicator for the presence of renal fibrosis." (PMID 39328595, 2024). "In conclusion, these findings imply that APC and ZBTB2 may contribute to the progression of renal fibrosis by mediating M2 macrophage infiltration." (PMID 39328595, 2024). "We hypothesize that APC and ZBTB2 are closely associated with M2 macrophage infiltration, and uncovering the role of APC and ABTB2 in M2 macrophage infiltration may unravel the physiopathological mechanisms underlying the development of renal fibrosis." (PMID 39328595, 2024). "Our study showed that the expression of APC and ZBTB2 was closely correlated with the abundance of M2 macrophages, suggesting that APC and ZBTB2 may exacerbate renal fibrosis through infiltration of M2 macrophages." (PMID 39328595, 2024). "Therefore, in delaying renal fibrosis, we speculate that APC and ZBTB2 may be potential therapeutic targets." (PMID 39328595, 2024). "Unfortunately, there are no relevant studies to investigate the role of ZBTB2 in renal fibrosis." (PMID 39328595, 2024).
thyroid cancer (1 paper, 2021). "Overall, our results suggest that AUF1 affecting thyroid cancer cells via regulating the expression of ZBTB2 and subsequent TRIM58 expression in vitro." (PMID 34222000, 2021). "Moreover, online database as well as the local data demonstrated the positive coexpression of TRIM58 and ZBTB2 in thyroid cancer tissues." (PMID 34222000, 2021).
thyroid tumor (1 paper, 2021). A benign or malignant neoplasm affecting the thyroid gland. "Results showed that AUF1 expression was increased, while ZBTB2 and TRIM58 was reduced in human thyroid tumors, when compared with those in peripheral normal tissues." (PMID 34222000, 2021).
uremia (1 paper, 2024). A clinical syndrome associated with the retention of renal waste products or uremic toxins in the blood. "For genes with stable expression in uremia, we overlapped the genes obtained by LASSO and SVM-RFE algorithms to obtain three genes, including ZBTB2, APC, and ERLIN2." (PMID 39328595, 2024).
cancer (3 papers, 2021 to 2022). A tumor composed of atypical neoplastic, often pleomorphic cells that invade other tissues. "Here we show ZASC1 interacts with ZBTB2, another cellular transcription factor with strong links to cancer." (PMID 33635925, 2021). "CRC cell-derived miR-146a-5p and miR-155-5p can be taken up by cancer-associated fibroblasts (CAFs) via sEVs and act through the JAK2-STAT3/NF-KB signaling pathway to suppress suppressor of cytokine signaling 1 (SOCS1) and zinc finger and BTB domain-containing 2 protein (ZBTB2)." (PMID 36552835, 2022).
psychiatric disorder (1 paper, 2018). A disorder characterized by behavioral and/or psychological abnormalities, often accompanied by physical symptoms. "But the report about the association of ZBTB2 with psychiatric disorder was not much." (PMID 29769613, 2018).
ZBTB2 also shares sentences with these, for which no sentence is quoted: tumor (7 papers); breast tumors (1); cervical cancer (1); glioma (1); melanoma (1).